INS (insulin)
Diseases named in the same sentence as INS in open-access papers (continued):
Sharing a sentence is not in itself a finding about the gene and the disease.
Insulin resistance (continued). "Though some evidence contradicted these early findings, the notion that Trib3 regulates insulin signaling was bolstered by the identification of a human Q84R SNP in Trib3 associated with insulin resistance and type 2 diabetes." (PMID 25329475, 2014). "It is caused by insulin resistance and insulin secretion impairment induced gradually and mainly by high blood glucose in conjunction with other factors such as obesity, aging, genetic predisposition, and physical inactivity." (PMID 25019091, 2014). "These include obesity, dyslipidemia with an increase in total triglycerides, total cholesterol, and increased insulin and insulin:glucose ratio, which suggests a susceptibility to insulin resistance." (PMID 24628878, 2014). "Insulin resistance is a condition where the body has a reduced ability to respond to the insulin hormone which can cause blood glucose to rise above normal levels." (PMID 24681553, 2014). "GSK-3β impairs the ability of insulin to activate glucose disposal and over-expression is associated with insulin resistance." (PMID 24520329, 2014). "Previous studies have suggested that liver fat accumulation is associated with absolute increases in insulin secretion from the beta-cell, in order to compensate for insulin resistance and maintain euglycaemia." (PMID 24669786, 2014). "The exposure to excess insulin can not only aggravate insulin resistance and lead to loss of endogenous pancreatic islets as observed in this study, but also lead to many other severe consequences." (PMID 24741073, 2014). "The rs9997745 SNP in ACSL1 we identified has been previously associated with metabolic syndrome, fasting glucose, insulin levels, and insulin resistance." (PMID 25549360, 2014). "At a cellular level, TNF-dependent activation of stress-related kinases inhibits insulin signaling, causing cellular insulin resistance." (PMID 24563869, 2014). "It has been well conceived that dietary carbs can increase insulin secretion, which subsequently stimulate lipogenesis and then cause insulin resistance." (PMID 25055153, 2014). "The aim of this study was to examine the association between ectopic fat and organ-specific insulin resistance (IR) in insulin-target organs in patients with nonalcoholic fatty liver disease (NAFLD)." (PMID 24651470, 2014). "Phosphorylation of Ser-312 causes IRS-1 proteasomal degradation that leads to insulin resistance under both pathological and physiological conditions, while phosphorylation of Ser-616 is supposed to inhibit insulin activation of PI3-kinase." (PMID 25580119, 2014). "Higher n-3 LC-PUFA levels have been associated with improved insulin action, while higher saturated fatty acids levels have been associated with insulin resistance." (PMID 24454790, 2014). "We also sought associations between VAT, blood lipids, glucose, insulin and insulin resistance in this population." (PMID 24504765, 2014). "Insulin resistance is thus associated with reduced responses to insulin signaling in the IR/IRS-1/PI3K and greatly with IGF1 in the IGF1R/IRS-2/PI3K signaling pathways." (PMID 25346723, 2014). "In mouse models of obesity-induced insulin resistance, oral administration of curcumin has beneficial effects on the inflammatory response and decreased insulin sensitivity associated with high fat feeding." (PMID 24967364, 2014). "Further, the association between fasting vaspin levels and insulin resistance markers (glucose, insulin and HOMA) is also controversial." (PMID 25340725, 2014). "As the chemerin-Cmklr1 system has previously been implicated in the development of insulin resistance, we next assessed the glucose tolerance and insulin sensitivity in WT and Cmklr1-/- mice fed a HFC diet for 12 weeks." (PMID 24781986, 2014). "On the other hand, the increased in ALT has been associated with systemic and hepatic insulin resistance, along with increase in the secretion of insulin and reduces insulin clearance from the liver." (PMID 24919841, 2014).
Insulin resistance (continued). "Among the baseline characteristics assessed in the present study, only fasting insulin and insulin resistance (presented by HOMA-IR) were significantly associated with increase in BDNF." (PMID 24524285, 2014). "Increased postprandial endotoxemia is associated with markers of insulin resistance, probably explaining the strong association between the LPS-AUC and the body weight adjusted daily insulin dose." (PMID 24959195, 2014). "Generally, weight gain is the first step towards a state of insulin resistance, while higher insulin doses increase the risk of hypoglycemia, fluid retention, and congestive heart failure." (PMID 24738001, 2014). "Among diabetic statin users, HDL, LDL and total cholesterol were negatively correlated with executive function, whereas peripheral insulin levels and insulin resistance were negatively associated with attention." (PMID 24816647, 2014). "As an early hallmark of type 2 diabetes, the associated insulin resistance in peripheral tissues demands extra insulin production from the pancreatic β cells." (PMID 24944893, 2014). "Glucose tolerance tests (GTT) and insulin tolerance tests (ITT) also demonstrated that muscle specific loss of Lin28a led to insulin resistance and impaired glucose uptake." (PMID 25313561, 2014). "Although NASH is usually associated with insulin resistance, HF-fed Nrf2−/− mice exhibited better insulin sensitivity than HF-fed Nrf2+/+ mice." (PMID 24958099, 2014). "During the disease process in this animal model, values of HbA1c and fasting plasma insulin concentration rose progressively, primarily because this rat strain is genetically predisposed to hyperphagia, obesity, and insulin resistance." (PMID 24524730, 2014). "Insulin resistance, as estimated by fasting insulin and the HOMA index, was inversely associated with exercise capacity in our study population of patients with type 2 diabetes and CAD, being more pronounced in the subgroup with exercise-induced ischemia." (PMID 24612649, 2014). "Chronically elevated IL‐6 mediates inhibitory effects on insulin signaling and glucose metabolism, and therefore, has been linked to insulin resistance in peripheral tissues." (PMID 24997069, 2014). "Over time, impaired insulin secretion induced by statins worsens, more beta cells become unable to secrete sufficient insulin to compensate for insulin resistance with hyperinsulinemia, increasing the risk of developing Type 2 diabetes with longer statin use." (PMID 25022519, 2014). "Expression of adiponectin in adipose tissue is lower in subjects with obesity and insulin resistance than in lean subjects and is associated with higher degrees of insulin sensitivity and lower adipose TNF-α expression." (PMID 24733068, 2014). "In patients with type 1 diabetes insulin resistance is associated with the inability of insulin to decrease central aortic pressure, possibly predisposing to premature stiffening of large arteries." (PMID 24959195, 2014). "Insulin resistance is associated with hypofibrinolysis, and metformin has been shown to improve insulin sensitivity and fibrinolysis." (PMID 25510597, 2014). "It has been found that poor zinc status is associated with an increased risk of insulin resistance and that a higher content of zinc in the organism can improve insulin sensitivity." (PMID 23708056, 2014). "A positive association between circulating tryptase levels and insulin resistance parameters (HbA1c, insulin and HOMAIR) have been also found in our study, suggesting a glucose homeostasis impairment in those individuals with higher tryptase levels." (PMID 24830464, 2014). "They showed that in lean insulin-resistant subjects skeletal muscle insulin resistance predates hepatic insulin resistance and was associated with a 60% increase in plasma triglyceride." (PMID 26237598, 2014). "Although it results from synthetic action involving insulin resistance and impaired insulin secretion, a detailed aetiology underlying T2DM is still unclear." (PMID 25388378, 2014).
Insulin resistance (continued). "It has long been known that PTP1B is implicated in obesity, insulin resistance and type-2 diabetes mellitus by regulating insulin signaling." (PMID 24949727, 2014). "Obesity-induced inflammatory response impairs insulin signaling in insulin-responsive organs and causes systemic insulin resistance, which leads to a perturbation of glucose homeostasis and ultimately type-2 diabetes." (PMID 24895488, 2014). "Epidemiological studies found that several markers for insulin resistance and hyperinsulinemia, including high blood insulin, glucose, IGF-1, and C-peptide levels, are associated with the increased CRC risk." (PMID 25516230, 2014). "Adiponectin is produced by mature adipocytes; over-expression of adiponectin increases hepatic insulin sensitivity, while low levels of adiponectin are associated with insulin resistance and the metabolic syndrome." (PMID 25050734, 2014). "Modifications in insulin signaling, often associated with imbalances in energy homeostasis such as obesity, have been linked to a predisposition towards the development of insulin resistance." (PMID 25259572, 2014). "The CpG site with the strongest association with insulin and insulin resistance was also strongly associated with nearby single-nucleotide polymorphisms, implying that differences in genetic sequence can alter the epigenetic functionality of a genomic region." (PMID 25229548, 2014). "Defects in the activation of insulin-induced signalling cascades are often associated with insulin resistance, a characteristic feature of obesity and type 2 diabetes." (PMID 25058613, 2014). "Type 2 diabetes mellitus (T2DM) is a clinical syndrome characterized by elevated blood glucose caused by a combination of insulin resistance and progressive failure of insulin secretion by the β-cells in pancreatic islets of Langerhans." (PMID 25097548, 2014). "Houstis and colleagues show that ROS production precedes insulin resistance in cultured 3T3-L1 adipocytes and ROS scavenging rescues insulin sensitivity, providing evidence toward ROS as a primary cause of insulin resistance." (PMID 24672550, 2014). "Women carrying the same allele showed higher body fat mass, insulin and homeostasis model assessment of insulin resistance (HOMA-IR)." (PMID 24562334, 2014). "Lately, hepatic overexpression of ANGPTL8 has been shown to promote proliferation of pancreatic beta cells and increase insulin release in an insulin-deficient mouse model of insulin resistance." (PMID 24478758, 2014). "Such pathways include among other defects in insulin production, insulin resistance and clustering of cardiovascular risk factors and their neuro-toxic effects." (PMID 24661645, 2014). "In terms of the association of vitamin D and beta cell function and insulin resistance, there are several potential effects of vitamin D on pancreatic beta cell function and insulin action." (PMID 24868538, 2014). "Adiponectin (ADIPOQ), an insulin sensitizer secreted principally by adipocytes, is inversely associated with body fat, obesity, insulin resistance through the stimulation of insulin secretion, increment of fatty acid combustion and energy consumption." (PMID 25516230, 2014). "There is also a direct and strong association between ChREBP expression and insulin sensitivity in adipose tissue of humans with insulin resistance." (PMID 25054881, 2014). "Compared to insulin-sensitive obese subjects, insulin resistance is associated with differential gut microbiota profile in insulin-resistant obese subjects." (PMID 24608927, 2014). "It has been reported that higher 25(OH)D concentration is strongly associated with low insulin and insulin resistance in adults." (PMID 25551248, 2014). "Chronic hyperinsulinemia desensitizes peripheral tissues to insulin and causes systemic insulin resistance." (PMID 24563869, 2014).
Insulin resistance (continued). "The evidence shows a strong association between TG/HDL-C and insulin resistance as measured by glucose clamp, modified insulin suppression test, and homoeostasis model assessment index." (PMID 25300321, 2014). "Although there are a few exceptions, generally insulin resistance is believed to be the primary cause of NAFLD: insulin activates lipogenesis, accelerating FA synthesis and TG accumulation in the liver." (PMID 24473773, 2014). "Recently, obesity-induced insulin resistance in peripheral insulin target tissues has been linked to ER stress that results in abnormal activation of the UPR." (PMID 25398386, 2014). "Immune mediated destruction of pancreatic b-cells leads to insulin deficiency and eventually to type I diabetes, while type II diabetes is characterized by insulin resistance and relative deficiency in insulin signaling." (PMID 25105142, 2014). "This heterogeneous group of disorders is characterized by hyperglycemia and results from absolute insulin deficiency, insulin resistance and/or abnormal insulin secretion." (PMID 25089237, 2014). "Increased expression of SCD1 in the muscles of obese patients and rats leads to insulin resistance, while its deficiency in mice improves insulin sensitivity and prevents hepatosteatosis." (PMID 25402228, 2014). "Insulin resistance is a characteristic metabolic defect that precedes overt β-cell dysfunction and is primarily associated with resistance to insulin-mediated glucose disposal at the periphery and compensatory hyperinsulinemia." (PMID 24151620, 2013). "When mice were challenged with HFD, which increases the risk of obesity and insulin resistance, we observed that insulin levels were significantly decreased when compared to WT mice fed under the same diet." (PMID 23336009, 2013). "Increased hepatic steatosis is associated with impaired insulin clearance and hepatic insulin resistance, which results in plasma glucose elevation, compensatory hyperinsulinemia and progression to type 2 DM." (PMID 23688034, 2013). "Resistin was first identified in a screen for proteins that were down-regulated by the insulin-sensitizing antidiabetic drug rosiglitazone, and it was shown to cause insulin resistance." (PMID 24072088, 2013). "CES1 gene duplication was positively associated with insulin sensitivity (P = 0.05) as well as glucose tolerance (P = 0.03) and negatively associated with homeostasis model assessment-insulin resistance (P = 0.02)." (PMID 23468884, 2013). "Several studies have demonstrated that NAFLD is associated with insulin resistance leading to a resistance in the antilipolytic effect of insulin in the adipose tissue with an increase of free fatty acids (FFAs)." (PMID 23666091, 2013). "In the current report, we show for the first time an association between COBLL1 rs7607980 C allele, lower insulin levels and lower insulin resistance in overweight and obese children." (PMID 23463496, 2013). "Our major findings were: (i) The high mRNA levels of TXNIP in bone from CS patients were significantly associated with high levels of glucose and insulin, increased insulin resistance, and decreased insulin sensitivity in these patients." (PMID 23691179, 2013). "In this review, we will summarize the available data on variants of genes encoding for insulin-signaling inhibitor molecules and their association with insulin resistance and related diseases." (PMID 23762820, 2013). "Insulin resistance has been shown to be associated with impaired endothelial function, and there is a close correlation between insulin sensitivity and basal insulin production in healthy subjects." (PMID 23964054, 2013). "Fat deposition in muscle is often thought to be associated with insulin resistance, and selective reduction of intramyocellular lipid restores normal insulin signaling, reverting to a healthy metabolic state." (PMID 24772374, 2013).
Insulin resistance (continued). "Disruption of adiponectin causes a phenotype of insulin resistance in mice and over-expression of adiponectin improves insulin sensitivity wild-type and leptin deficient obese mice." (PMID 23826141, 2013). "Lcmt1−/− animals displayed significantly decreased glucose tolerance despite higher insulin levels, a pattern often associated with insulin resistance." (PMID 23840384, 2013). "Extracolonic manifestations of carrageenan exposure leading to inflammation and impaired insulin signaling in the mouse liver were associated with glucose intolerance and insulin resistance in recent experiments." (PMID 23766559, 2013). "Patient B demonstrated fasting insulin levels higher than patient A probably due to underlying insulin resistance." (PMID 23424590, 2013). "Hyperglycemia and insulin resistance are determinants of cardiovascular risk with fasting blood glucose and insulin concentrations being directly predictive for future cardiovascular events." (PMID 23953602, 2013). "Achieving and maintaining glycemic control in type 2 diabetic patients is challenging due to the gradual loss of endogenous insulin secretion and the presence of insulin resistance." (PMID 23617853, 2013). "For one thing, insulin resistance, resulting in compensatory hyperinsulinemia in type 2 diabetes, is associated with the abnormity of insulin/insulin receptor-mediated signal transduction." (PMID 24386004, 2013). "At least one in four insulin-naïve people with type 2 diabetes is reluctant to start insulin therapy and this process of psychological insulin resistance is associated with the presence of depressive symptoms." (PMID 24223860, 2013). "Ceramide also modulates many of the insulin signaling intermediates such as insulin receptor substrate, Akt, Glut-4, and it causes insulin resistance." (PMID 23835113, 2013). "e.g. genome-wide study of the genetic basis of insulin resistance reported that a variant of AKAP6 was associated with BMI-adjusted fasting insulin (5×10-7) in a meta-analysis cohort of European descent." (PMID 23628382, 2013). "There is ample evidence that increases of plasma FFA concentrations cause hepatic insulin resistance, impair insulin signaling, and stimulate hepatic glucose production by driving both hepatic gluconeogenesis and glycogenolysis." (PMID 23653642, 2013). "A strong body of evidence suggests that regular exercise without calorie restriction or weight loss is associated with reduced insulin resistance as well as improved insulin sensitivity in overweight and obese adults." (PMID 24454364, 2013). "Weight loss after an exercise program and bariatric surgery results in a decrease in visfatin levels along with improvement in insulin sensitivity, indicating a compensatory mechanism in response to hyperglycemia associated with insulin resistance." (PMID 24145612, 2013). "A defect in the activation of insulin-related signal events is associated with the development of insulin resistance and glucose intolerance." (PMID 23452929, 2013). "In Caucasian patients with type 2 diabetes who were also overweight and middle-aged, leptin levels were significantly associated with insulin secretion and insulin resistance, and with insulin secretion in patients undergoing oral drug therapy." (PMID 23853613, 2013). "TNF-α interferes on insulin metabolism cascade, activating proinflammatory pathways that impair insulin signalling at the level of the insulin receptor substrate proteins, causing insulin resistance." (PMID 23919592, 2013). "Consistent with this view it has been observed that fat deposition in insulin effector cells (liver cells, muscle cells, and adipocytes) decreases their sensitivity to insulin, causing insulin resistance." (PMID 23557393, 2013). "Dolphins from this study’s managed collection are at higher risk of insulin resistance and metabolic syndrome, including higher postprandial insulin, glucose, cholesterol, and triglycerides compared to the free-ranging group in this study." (PMID 24137158, 2013).